YEATS2 (YEATS domain containing 2)
Description:
Chromatin reader component of the ATAC complex, a complex with histone acetyltransferase activity on histones H3 and H4. YEATS2 specifically recognizes and binds histone H3 crotonylated at 'Lys-27' (H3K27cr). Crotonylation marks active promoters and enhancers and confers resistance to transcriptional repressors.
Synonyms: KIAA1197; FLJ10201; FLJ12841; FLJ13308; FAME4
Tractability: PROTAC: UniProt records ubiquitination sites on it; ubiquitination databases record sites on it; its protein half-life has been measured.
Target class: YEATS domain; Epigenetic regulator; Reader
Chemical probes: PFI-8 (high quality)
Gene: Protein-coding gene on chromosome 3 (183,697,748 to 183,812,805, forward strand). Ensembl gene ENSG00000163872.
Subcellular location: Nucleus
Subcellular location (Human Protein Atlas): Nucleoplasm
Pathways (Reactome):
Chromatin organization: HATs acetylate histones
Gene expression (Transcription): Formation of WDR5-containing histone-modifying complexes
Gene Ontology:
Molecular function: histone binding; histone reader activity; modification-dependent protein binding; protein binding; TBP-class protein binding; transcription corepressor activity
Biological process: negative regulation of transcription by RNA polymerase II; regulation of cell cycle; regulation of cell division; regulation of DNA-templated transcription; regulation of transcription by RNA polymerase II; regulation of tubulin deacetylation; chromatin remodeling; regulation of embryonic development
Cellular component: ATAC complex; mitotic spindle; nucleoplasm; nucleus
Genetic constraint (gnomAD): Loss-of-function variants: 65 observed, 144.86 expected, observed/expected ratio (o/e) 0.45, 90% interval 0.37 to 0.55. The upper end of that interval is the gene's LOEUF score, 0.55, which puts it in group 2 of 6, group 1 being the genes least tolerant of losing a copy. Missense variants: 1,472 observed, 1,702.2 expected, observed/expected ratio (o/e) 0.86, 90% interval 0.83 to 0.9. Synonymous variants: 611 observed, 642.85 expected, observed/expected ratio (o/e) 0.95, 90% interval 0.89 to 1.02.
Homologues: Orthologues: chimpanzee YEATS2 (99% identical), macaque YEATS2 (96% identical), dog YEATS2 (93% identical), rabbit YEATS2 (93% identical), pig YEATS2 (90% identical), guinea pig YEATS2 (89% identical), mouse Yeats2 (86% identical), rat Yeats2 (84% identical), zebrafish yeats2 (54% identical), tropical clawed frog yeats2 (53% identical), Drosophila melanogaster D12 (17% identical). Paralogues in human: MLLT1 (10% identical), MLLT3 (9% identical).
Diseases named in the same sentence as YEATS2 in open-access papers:
YEATS2 is named in the same sentence as 32 diseases in open-access papers, as found by Europe PMC text mining. Sharing a sentence is not in itself a finding about the gene and the disease. The quoted sentences say what the papers report.
lung cancer (9 papers, 2017 to 2025). A malignant neoplasm involving the lung. "Similarly, YEATS2 within the ATAC complex has been linked to non—small cell lung cancers that bear YEATS2 gene amplifications." (PMID 39222683, 2024). "As expected, the YEATS2-WT cells produced much larger tumors compared with the T604A mutants, suggesting that YEATS2 O-GlcNAcylation enhances lung cancer, probably via promoting H3K9ac and its targeting genes." (PMID 40541806, 2025). "Taken together, our work suggests that YEATS2 O-GlcNAcylation promotes its chromatin association, subsequent ATAC-dependent ribosomal gene expression, and tumorigenesis of lung cancer." (PMID 40541806, 2025). "In sum, we report the O-GlcNAcylation of a histone reader, YEATS2, and its physiological role in lung cancer." (PMID 40541806, 2025). "This interaction significantly alters the transcriptional program, which is essential for lung cancer tumorigenesis.YEATS2 is not only amplified in lung cancer but also required for the growth and survival of cancer cells." (PMID 39991629, 2025). "Research has shown that YEATS2 is highly amplified in human lung cancer and is essential for cancer cell growth and survival." (PMID 39991629, 2025). "YEATS2 has previously been found to promote tumorigenesis in lung cancer by colocalizing with H3K27 acetylation, facilitating the transcription of essential genes for cell multiplication." (PMID 39202022, 2024). "The high expression of YEATS2 heralded the poor prognosis of lung cancer patients, which is consistent with our findings." (PMID 36503492, 2022). "The YEATS2 gene has been confirmed to be highly amplified in human nonsmall cell lung cancer (NSCLC) and is required for cancer cell growth and survival." (PMID 33398034, 2021). "In clonogenic assay of both H1299 and A549 cells, the YEATS2 KD cells developed fewer colonies compared with the control cells, suggesting that YEATS2 is required for lung cancer cell survival." (PMID 29057918, 2017). "Taken together, these results indicate that YEATS2 is required for cell growth, survival, and transformation of lung cancer cells." (PMID 29057918, 2017). "Besides lung cancer, YEATS2 is also found to regulate other kinds of cancer, such as pancreatic cancer, hepatocellular carcinoma, and head and neck squamous cell carcinoma." (PMID 40541806, 2025). "Finally, xenograft experiments show that YEATS2 O-GlcNAcylation promotes tumorigenesis in lung cancer." (PMID 40541806, 2025). "Furthermore, xenograft experiments show that YEATS2 O-GlcNAcylation promotes lung cancer tumorigenesis." (PMID 40541806, 2025). "It is known that YEATS2 links histone acetylation with lung cancer tumorigenesis." (PMID 40541806, 2025). "We next assessed YEATS2 expression levels across a number of lung cancer cell lines." (PMID 29057918, 2017). "Since YEATS2 is highly amplified in NSCLC, we sought to determine whether depletion of YEATS2 affects lung cancer cell growth." (PMID 29057918, 2017). "YEATS2, a YEATS domain‐containing protein, has been increasingly recognized for its critical role in the pathogenesis of lung cancer." (PMID 39991629, 2025). "Knockdown of YEATS2 dampens the expression of 49 out of the total 79 ribosomal protein genes and suppresses the growth and survival of a panel of lung cancer cells, suggesting a growth dependency of NSCLC on YEATS2, and possibly the ATAC complex." (PMID 29057918, 2017). "Hence, YEATS2 is likely an important factor in CLL development, as with lung cancer, and further investigation is required to elucidate its role." (PMID 39202022, 2024). "YEATS2 is a histone H3K27 acetylation reader, which can bind to acetylated histone H3 through the YEATS domain, and it was considered a connector between histone acetylation and lung cancer." (PMID 36503492, 2022).
lung cancer (continued). "The YEATS domain of YEATS2 binds to acetylated histone H3K27 and recruits the ATAC complex to chromatin to write H3K9ac on promoters, which in turn maintains an open and acetylated chromatin environment to promote the expression of ribosomal protein genes and lung cancer tumorigenesis." (PMID 40541806, 2025). "However, how YEATS2 is involved in the malignant phenotypes of lung cancer has not been fully clarified." (PMID 36503492, 2022).
pancreatic cancer (9 papers, 2017 to 2025). "As a consequence of this function, YEATS2 overexpression has been linked with various types of cancer, including non-small cell lung cancer, head and neck squamous cell carcinoma, and pancreatic cancer." (PMID 39202022, 2024). "TNF-α induced Tyrosine dephosphorylation of the YEATS domain increases MYC eRNA binding to the YEATS2 protein in pancreatic cancer cells." (PMID 40216980, 2025). "Some research have found that YEATS domain-containing 2 (YEATS2) is highly expressed in non-small cell lung cancer and pancreatic cancer, whereas its function in HNSCC is left to be studied." (PMID 34587874, 2021). "It was confirmed that YEATS2 was the target gene of hypoxia-inducible factor 1α (HIF1α) and abundantly expressed in pancreatic cancer tissues, which was related to poor prognosis." (PMID 34587874, 2021). "According to previous studies, YEATS2 could play a carcinogenic role in pancreatic ductal adenocarcinoma, pancreatic cancer, and non-small cell lung cancer." (PMID 40040791, 2025). "Overexpression of YEATS2 promotes the proliferation and migration of pancreatic cancer cells." (PMID 36980736, 2023). "In addition, YEATS2 accelerated cell proliferation and migration in pancreatic cancer in vitro." (PMID 34587874, 2021). "Notably, both downregulated and upregulated genes were enriched in pathways in cancers, including lung, colorectal, and pancreatic cancers, suggesting that YEATS2 controls growth and survival of various types of tumors through transcriptional regulation of essential genes." (PMID 29057918, 2017). "MYC eRNAs dynamically interact with YEATS2 protein and recruit the YEATS2-containing ATAC complex to the MYC promoter to induce MYC gene transcription in pancreatic cancer." (PMID 40216980, 2025). "It has been reported that YEATS2 can act as a target of HIF1α and regulate the TAK1/NF-κB pathway to promote tumor progression in pancreatic cancer." (PMID 36980736, 2023).
non-small cell lung carcinoma (6 papers, 2017 to 2025). A group of at least three distinct histological types of lung cancer, including non-small cell squamous cell carcinoma, adenocarcinoma, and large cell carcinoma. "YEATS2 has been reported to be associated with the progression of non-small-cell lung cancer through histone acetylation." (PMID 36980736, 2023). "The activity of the ATAC complex has also been associated with non-small cell lung cancer tumorigenesis, with the YEATS2 subunit being highly amplified in clinical non-small cell lung cancer samples." (PMID 35740643, 2022). "We found that the YEATS2 gene is highly amplified in human cancers including non-small cell lung cancer (NSCLC)." (PMID 29057918, 2017). "Here, the authors identify YEATS2 as a histone H3K27ac reader, regulating a transcriptional program essential for tumorigenesis in human non-small cell lung cancer." (PMID 29057918, 2017). "Moreover, in non-small cell lung cancer, YEATS2 acted as a histone H3K27ac reader, orchestrating a transcriptional program critical for tumorigenesis." (PMID 39202022, 2024). "In addition, studies have shown that YEATS2 is related to the occurrence of non-small-cell lung cancer." (PMID 36980736, 2023).
head and neck squamous cell carcinoma (4 papers, 2017 to 2025). A squamous cell carcinoma that arises from any of the following anatomic sites: lip and oral cavity, nasal cavity, paranasal sinuses, pharynx, larynx, and salivary glands. "As part of the 3q26 amplicon, YEATS2 is highly amplified in a variety of human cancers, including lung squamous cell carcinoma (56% amplification frequency), ovarian serous cystadenocarcinoma (27%), and head and neck squamous cell carcinoma (23%)." (PMID 29057918, 2017).
hepatocellular carcinoma (3 papers, 2023 to 2025). A malignant tumor that arises from hepatocytes. "Mechanistically, it has been found in previous studies that YEATS2 overexpression stimulated the PI3K/AKT pathway and altered the extracellular matrix structure, facilitating the proliferation, migration, and metastasis of hepatocellular carcinoma (HCC) cells." (PMID 39202022, 2024).
chondrosarcoma (2 papers, 2017 to 2024). A malignant cartilaginous matrix-producing mesenchymal neoplasm arising from the bone and soft tissue.
lymph node metastasis (2 papers, 2023). "Further, we analyzed the relationship between YEATS2 expression and lymph node metastasis." (PMID 36980736, 2023). "The results showed that patients with N1 lymph node metastasis had higher YEATS2 expression than N0 patients without lymph node metastasis." (PMID 36980736, 2023).
Wilms tumor (2 papers, 2021 to 2023). An embryonal neoplasm characterized by the presence of epithelial, mesenchymal, and blastema components. "Especially MYCN and PEG10 showed very similar patterns of expression in different subtypes of Wilms tumors, predominantly the high-risk blastemal type, where YEATS2 was also significantly overexpressed." (PMID 34689785, 2021). "A study finds YEATS2 may be linked to poor prognoses in Wilms tumors." (PMID 36980736, 2023). "Extended expression analysis in our own independent cohort of 299 Wilms tumors by qRT-PCR confirmed the correlated expression of PEG10 and YEATS2 with MYCN." (PMID 34689785, 2021). "Five of seven proven candidates, PEG10, YEATS2, FOXK1, CBLL1 and MCRS1 showed a clear positive correlation of mRNA levels with MYCN in Wilms tumors undergoing the SIOP protocol." (PMID 34689785, 2021).
esophageal squamous cell carcinoma (1 paper, 2025). Esophageal squamous cell carcinoma (ESCC) is a type of esophageal carcinoma (EC) that can affect any part of the esophagus, but is usually located in the upper or middle third. "We have found significant mutations and copy number amplifications of YEATS domain containing 2 (YEATS2) gene in esophageal squamous cell carcinoma (ESCC) through whole genome sequencing (WGS)." (PMID 40040791, 2025).
head and neck cancer (1 paper, 2025). A primary or metastatic malignant neoplasm affecting the head and neck. "Regulation of epithelial-to-mesenchymal transition (EMT) by YEATS2 is SP1-dependent in head and neck cancer (HNC)." (PMID 40810390, 2025). "YEATS2 regulates expression of epithelial-to-mesenchymal transition (EMT)-related SPARC in head and neck cancer (HNC)." (PMID 40810390, 2025). "On further investigation using immunoblotting, we found that the expression of YEATS2 protein was increased in a set of 23 head and neck cancer vs. matched normal tissues." (PMID 40810390, 2025). "We report that the histone reader YEATS2 is responsible for increased invasive potential in head and neck cancer in an SP1-dependent manner." (PMID 40810390, 2025). "YEATS2 drives epithelial-to-mesenchymal transition (EMT) in head and neck cancer cells." (PMID 40810390, 2025). "YEATS2 and glutaryl-CoA dehydrogenase (GCDH) regulate histone crotonylation in head and neck cancer (HNC)." (PMID 40810390, 2025). "Here, we investigated the interplay between a highly expressed epigenetic factor, YEATS2, and a metabolic enzyme, GCDH, in regulating epithelial-to-mesenchymal transition in head and neck cancer." (PMID 40810390, 2025). "In conclusion, we have presented a sophisticated interplay between YEATS2 and GCDH, where the upregulation of both factors contributes towards the enhancement of EMT in head and neck cancer by changes in the global EMT-favoring gene expression, mediated through promoter histone crotonylation." (PMID 40810390, 2025).
liposarcoma (1 paper, 2021). A usually painless malignant tumor that arises from adipose tissue. "This is consistent with recent findings identifying amplification of YEATS2 in sarcomas such as well differentiated liposarcoma and dedifferentiated liposarcoma." (PMID 33913810, 2021). "Amplification of YEATS2 has been identified in ovarian cancer, head and neck cancer, esophageal cancer, and uterine cancer, as well as both well-differentiated and dedifferentiated liposarcoma." (PMID 33913810, 2021).
liver cancer (1 paper, 2023). An epithelial or non-epithelial malignant neoplasm that arises from the liver. "Collectively, the findings showed that YEATS2 overexpression promoted the migration, invasion, and cycle of liver cancer cells." (PMID 36980736, 2023). "Overall, YEATS2 is closely related to cancer progression, but the role of YEATS2 in liver cancer is still unclear." (PMID 36980736, 2023). "Through GEO and TCGA database analysis, we found that YEATS2 was significantly highly expressed in liver cancer, which was consistent with our previous microarray analysis data of liver cancer tissue samples." (PMID 36980736, 2023). "The CCK-8 experiment showed that compared with the pc-Vector group, the proliferation ability of the cells in the pc-YEATS2 group was significantly enhanced, indicating that the overexpression of YEATS2 enhanced the growth of liver cancer cells." (PMID 36980736, 2023). "Our subsequent recovery experiments found that the PI3K inhibitor LY294002 reversed the promotion effect of YEATS2 on the migration and invasion of liver cancer cells and the expression of MMP7." (PMID 36980736, 2023). "Mechanistically, we revealed that YEATS2 promoted liver cancer progression by activating the PI3K/AKT signaling pathway and remodeling the extracellular matrix." (PMID 36980736, 2023). "In wound healing experiments, LY294002 partially counteracted the promoting effect of YEATS2 overexpression on the migration of liver cancer cells." (PMID 36980736, 2023). "Subsequently, we further explored the effect of YEATS2 on the biological behavior of liver cancer cells MHCC97H and SMMC-7721." (PMID 36980736, 2023). "According to the GSE14520 dataset, the expression of YEATS2 in liver cancer tissues was significantly higher than that in normal tissues, and patients with high expression of YEATS2 had worse prognoses." (PMID 36980736, 2023). "How YEATS2 specifically functions in liver cancer is the next goal of this study." (PMID 36980736, 2023). "In the study, we found that YEATS2 is upregulated in liver cancer." (PMID 36980736, 2023). "In addition, the TCGA database showed that the expression of YEATS2 in 373 liver cancer tissues was higher than normal samples." (PMID 36980736, 2023). "Targeting YEATS2 has the potential to be used as a treatment for liver cancer." (PMID 36980736, 2023). "This further confirmed that YEATS2 had a pro-proliferative effect on liver cancer cells." (PMID 36980736, 2023). "Furthermore, in our team’s previous microarray data analysis of tissue samples, it was shown that the expression of YEATS2 in liver cancer was higher than that in normal samples." (PMID 36980736, 2023). "Enrichment analysis results showed that YEATS2 may participate in the progression of liver cancer through the PI3K/AKT pathway and extracellular matrix organization." (PMID 36980736, 2023). "YEATS2 acts through the PI3K/AKT/MMP7 signaling pathway and affects the progression of liver cancer." (PMID 36980736, 2023). "To explore how YEATS2 participates in the progression of liver cancer, we first performed GO analysis and KEGG pathway enrichment analysis on the differentially expressed genes in the high-expression YEATS2 group and low-expression YEATS2 group." (PMID 36980736, 2023).
lung adenocarcinoma (1 paper, 2017). A carcinoma that arises from the lung and is characterized by the presence of malignant glandular epithelial cells. "To this end, we knocked down (KD) YEATS2 gene expression in the H1299 lung adenocarcinoma cell line using two independent shRNAs and determined cell growth." (PMID 29057918, 2017).
ovarian carcinoma (1 paper, 2017). A malignant neoplasm originating from the surface ovarian epithelium. "In human NSCLC and ovarian cancer patients, high YEATS2 expression levels are correlated with worse prognosis." (PMID 29057918, 2017).
pancreatic ductal adenocarcinoma (1 paper, 2025). An infiltrating adenocarcinoma that arises from the epithelial cells of the pancreas. "As a novel histone acetylation reader, YEATS2 has been reported to play an important tumor-promoting role in lung cancer, hepatocellular carcinoma and pancreatic ductal adenocarcinoma." (PMID 40040791, 2025).